IMP3 (IMP U3 small nucleolar ribonucleoprotein 3)
Diseases named in the same sentence as IMP3 in open-access papers (continued):
Sharing a sentence is not in itself a finding about the gene and the disease.
triple-negative breast carcinoma (5 papers, 2014 to 2024). An invasive breast carcinoma which is negative for expression of estrogen receptor (ER), progesterone receptor (PR), and human epidermal growth factor receptor 2 (HER2). "Survival analysis that we performed revealed that DFS interval and OS in patients with triple negative breast cancer is shorter in cases of high-clinical stage, presence of basal morphology, and strong IMP3 immunostaining." (PMID 32049813, 2020). "It is believed that the same mechanism of IMP3 specific T cell immune response represents a new possibility for the treatment of triple negative breast cancer." (PMID 32049813, 2020). "Depletion of IMP3 expression in triple-negative breast cancer cells increased significantly their sensitivity to doxorubicin and mitoxantrone." (PMID 32049813, 2020). "TRPS1 was also found to be positively related with IMP3, which is expressed preferentially in triple negative breast cancers (TNBC)." (PMID 24934762, 2014). "According to our results, determination of IMP3 biomarker, may serve as independent prognostic factor within the heterogeneous group of triple negative breast cancer." (PMID 32049813, 2020). "Interestingly, there is some evidence that IMP3 could be used to assess chemosensitivity in triple-negative breast cancers." (PMID 37627115, 2023). "According to results of our study IMP3 expression can be used as negative prognostic factor for triple negative breast carcinomas." (PMID 32049813, 2020). "Based on the Cox regression analysis, our study showed that increased expression of IMP3 is a negative predictive factor for the prognosis of triple negative breast cancer." (PMID 32049813, 2020). "Targeting IMP3 molecule could be an effective approach to the management of a triple negative breast cancer with new immunological therapies, which does not yet exist for this group of tumors." (PMID 32049813, 2020).
glioblastoma (4 papers, 2015 to 2022). The most malignant astrocytic tumor (WHO grade IV). "In glioblastomas IMP3 also promotes cell proliferation, migration and invasion by inducing epithelial-mesenchymal transition." (PMID 34997006, 2022). "The only previous study about IMP3 protein expression in adult gliomas focused just on glioblastomas and identified IMP3 as a GBM-specific marker of tumour aggressiveness and of poor prognosis." (PMID 25695077, 2015). "Previous studies identified IMP3 as a glioblastoma-specific marker and as a prognostic factor in series of 83 glioblastomas and in a series of 77 pediatric pilocytic and pilomyxoid astrocytomas, though only in the latter confirmed by multivariate analysis." (PMID 25695077, 2015). "Overall, IMP3 expression was higher in glioblastomas (68%) than in grade III tumors (20%, P < 0.0001), and IMP3-positive high-grade gliomas showed a shorter overall and disease-free survival than negative ones (P = 0.0002 and P = 0.006, resp)." (PMID 25695077, 2015). "High Ki67 levels were correlated with better prognosis in glioblastomas but IMP3 expression was not correlated with the proliferation index." (PMID 25695077, 2015).
glioma (4 papers, 2015 to 2023). A benign or malignant brain and spinal cord tumor that arises from glial cells (astrocytes, oligodendrocytes, ependymal cells). "IMP3 has been shown to overexpress in glioma cells, and its expression modulation has been linked to glioma grading." (PMID 38072944, 2023). "Since GSCs show enhanced migratory property and IMP3 promotes migration of glioma cells, we were intrigued if there is any association between IMP3-p65 cascade and GSCs." (PMID 28465487, 2017). "In relation to molecular characteristics of high-grade gliomas, we correlated IMP3 protein expression with IDH1 mutational and MGMT methylation status." (PMID 25695077, 2015). "The aim of this study was to evaluate clinical significance of the immunohistochemical expression of IMP3 in high-grade gliomas and to investigate its role as a diagnostic and prognostic biomarker." (PMID 25695077, 2015). "The data suggest that IMP3 staining could identify a subgroup of patients with poor prognosis and at risk of recurrence in high-grade gliomas." (PMID 25695077, 2015). "Our results suggest that IMP3 staining could increase the accuracy of histological diagnosis and tumor grading and could identify a subgroup of patients with poor prognosis and at a higher risk of recurrence in high-grade gliomas." (PMID 25695077, 2015). "p65, a subunit of the heterodimer of nuclear factor-κ B, is an essential regulator of glioma cell migration promoted by IMP3." (PMID 38072944, 2023). "IMP3 has been found to promote cell migration in glioma by increasing the levels of p65 protein (RELA; subunit of NF-κB heterodimer), but without modifying transcript levels." (PMID 34997006, 2022). "IMP3 silencing also resulted in the downregulation of four glioma reprogramming transcription factors- OLIG2, POU3F2, SOX2 and SALL2 in GSCs." (PMID 28465487, 2017). "Previously published report from our group demonstrated that IMP3 depletion results in enhanced sensitivity to chemotherapy in glioma cell lines." (PMID 28465487, 2017). "We found a positive enrichment of upregulated genes in CD133+ glioma cells (CD133+_up) in GBMs with high levels of IMP3 transcripts (IMP3 high)." (PMID 28465487, 2017). "Our p65 rescue experiment in IMP3 depleted U138 glioma cells clearly reflects the importance of the molecule downstream to IMP3 in imparting migratory potential to these cells." (PMID 28465487, 2017). "In contrast, GBM tumors with low levels of IMP3 transcripts (IMP3 low) had a positive enrichment of downregulated genes in CD133+ glioma cells (CD133+_down)." (PMID 28465487, 2017). "To experimentally demonstrate that p65 is a target of IMP3, we measured the p65-dependent luciferase activity in glioma cells after modulating IMP3 levels." (PMID 28465487, 2017). "This study establishes p65 as a novel target of IMP3 in increasing glioma cell migration and underscores the significance of IMP3-p65 feedback loop for therapeutic targeting in GBM." (PMID 28465487, 2017). "Taken together, these results underscore the importance of IMP3-p65 cascade in maintenance of glioma stem-like cells and their migratory capacity." (PMID 28465487, 2017). "Exogenous overexpression of IMP3 in LN229 glioma cells increased luciferase activity in a concentration dependent manner, while knockdown of IMP3 in U87, T98G and U138 cells led to a significant reduction in the activity from NF-κB dependent reporter." (PMID 28465487, 2017). "We have thus, delineated IMP3- NF-κB cascade by which IMP3 contributes in migration of glioma bulk and stem-like cells." (PMID 28465487, 2017). "Current study establishes that IMP3 is critical for migration of both differentiated and glioma stem-like cells." (PMID 28465487, 2017). "The exogenous overexpression of 3′UTR-less p65 significantly alleviated the inhibition of neurosphere formation observed in IMP3 silenced glioma stem-like cells." (PMID 28465487, 2017).
glioma (continued). "An integrative bioinformatics analysis identified p65 (RELA), a subunit of NF-κB heterodimer as a target and an important mediator of IMP3 promoted glioma cell migration." (PMID 28465487, 2017). "Our findings in glioma cells with IMP3 overexpression and silencing unequivocally establish IMP3 as a positive modulator of NF-κB signalling by increasing the translation of p65 transcript." (PMID 28465487, 2017). "Collectively, these results establish p65 as a target of IMP3 in mediating its pro-migratory functions in glioma cells." (PMID 28465487, 2017). "In this study, we have identified p65 (RelA) as a mediator of IMP3 functions including migration of glioma cell lines and maintenance of GSCs." (PMID 28465487, 2017). "Exogenous overexpression of p65 from a 3′UTR-less construct rescued the reduced migration of glioma cells in IMP3 silenced condition." (PMID 28465487, 2017). "In this study, we examined IMP3 protein expression in a series of human gliomas, correlating our results with molecular parameters and Ki67 proliferative index." (PMID 25695077, 2015). "In this context, our study, together with in silico evidences, demonstrates that IMP3 plays a role in glioma progression and its elevated expression identifies a subset of HGG patients with shorter survival times independently of the tumour grade." (PMID 25695077, 2015). "Additionally, a dominant negative form of IκB (IκBSR), an inhibitor of NF-κB pathway, decreased IMP3 transcript levels in U251 and U87 glioma cells." (PMID 28465487, 2017). "To confirm the association between IMP3 and GSCs, we carried out Gene Set Enrichment Analysis (GSEA) for the possible enrichment of gene expression profile of CD133+ (a marker for glioma stem-like cells) glioma cells, in IMP3 expressing glioma tumors." (PMID 28465487, 2017). "From the multiple targets, we were interested to identify a global regulator, regulated by IMP3 at the level of translation, which may be playing a crucial role in migration of glioma cells." (PMID 28465487, 2017). "In this work, we set out to identify IMP3 targets that promote glioma cell migration." (PMID 28465487, 2017). "Thus our study establishes that the intricate regulation between IMP3 and NF-κB pathway is essential for migration of glioma cells." (PMID 28465487, 2017). "We next investigated whether IMP3 expression could be a prognostic marker for high-grade gliomas, and we found that immunoreactive IMP3-HGG showed a shorter overall and disease-free survival than IMP3-negative cases (P = 0.0002 and P = 0.006, resp.)." (PMID 25695077, 2015). "To investigate whether IMP3 could be one of these markers, we looked for a correlation between IMP3 immunohistochemical expression and Ki67 labeling index in the high-grade gliomas." (PMID 25695077, 2015). "In addition, IMP3 silencing inhibited glioma stem-like cell maintenance and migration." (PMID 28465487, 2017). "In conclusion, this is the first study that investigates the immunohistochemical expression of the IMP3 protein with a correlation with other important parameters (IDH1 mutation and MGMT methylation status) and Ki67 proliferative index in a large series of high-grade gliomas." (PMID 25695077, 2015). "IMP3 expression could be evaluated in all 165 patients affected by primary gliomas." (PMID 25695077, 2015). "IGF2 mRNA-binding protein 3 (IMP3), a GBM upregulated RNA binding protein, promotes glioma cell migration." (PMID 28465487, 2017). "The present study examined the expression of the oncofetal protein IMP3 in a series of 135 patients affected by high-grade (grade III and IV) gliomas, correlating the results with proliferative activity, molecular parameters, and clinical and follow-up data." (PMID 25695077, 2015). "IMP3 can also enhance p65 expression and activate the NF-κB signaling pathway by specifically binding to sites on the p65 mRNA 3'UTR, which in turn promotes metastatic migration of glioma cells." (PMID 38072944, 2023).
glioma (continued). "IMP3 expression was significantly associated with the absence of mutations of IDH1 gene (P = 0.0001) and with the unmethylated phenotype of MGMT in high-grade gliomas (P = 0.004)." (PMID 25695077, 2015).
lung adenocarcinoma (4 papers, 2012 to 2022). A carcinoma that arises from the lung and is characterized by the presence of malignant glandular epithelial cells. "In this study we analysed expression of IMP3 in histological subtypes of lung adenocarcinoma and its impact on clinical staging." (PMID 23190601, 2012). "Further series are needed to confirm these results and eventually establish IMP3 in initial immunohistochemical panel for small bronchoscopic biopsy/cytology, as a marker for aggressive behaviour and higher metastatic potential of lung adenocarcinoma." (PMID 23190601, 2012). "In the present study expression of IMP3 was correlated with expression of TTF-1 and Napsin A, histological subtype and clinical stage of lung adenocarcinoma." (PMID 23190601, 2012). "Expression of oncofetal protein IMP3 correlates with distant metastases regardless of histological subtype of lung adenocarcinoma." (PMID 23706092, 2013). "Expression of IMP3 correlates with solid subtype and with distant metastases regardless of histological subtype of lung adenocarcinoma." (PMID 23190601, 2012).
lung carcinoma (4 papers, 2016 to 2025). "Collectively, we revealed that FTO drives lung cancer progression via m6A‐dependent sequestration of IGFBP3 mRNA into P‐bodies by IMP3, which suppresses translation and activates AKT signalling." (PMID 40621649, 2025). "Evidence from an in vitro IMP-3 knockdown research and from IMP-3 administration in lung cancer patients illustrated that IMP-3 may be a therapeutic target for malignancies." (PMID 26796627, 2016).
pancreatic ductal adenocarcinoma (4 papers, 2015 to 2024). An infiltrating adenocarcinoma that arises from the epithelial cells of the pancreas. "Over-expression of insulin-like growth factor 2 mRNA binding protein 3 (IMP3) is correlated with poor prognosis in pancreatic ductal adenocarcinoma (PDAC)." (PMID 25886367, 2015). "In pancreatic ductal adenocarcinoma cells, IMP3 modulates miRNA-mRNA interactions." (PMID 34997006, 2022).
squamous cell carcinoma (4 papers, 2020 to 2026). A carcinoma arising from squamous epithelial cells. "Higher IMP3 expression represented a significantly worse prognosticator for clinical outcomes of patients with squamous cell carcinoma of the larynx." (PMID 34503117, 2021). "To date, there have been no data on IMP3 expression and clinical outcome in high-risk localisations (lip, ear) of squamous cell carcinoma of the skin." (PMID 37627115, 2023). "Several studies have revealed the expression of IMP3 in squamous cell carcinoma which supports this hypothesis." (PMID 32692399, 2020).
cervical squamous cell carcinoma (3 papers, 2020 to 2025). A squamous cell carcinoma arising from the cervical epithelium. "Consistent with previous reports, IMP3 has been shown to cooperate with circCDKN2B-AS1 to promote aerobic glycolysis in cervical squamous cell carcinoma." (PMID 41614778, 2025). "For oSCC and also for squamous cell carcinoma of the uterine cervix, a significant correlation between IMP3 and LNMs has been shown." (PMID 37627115, 2023).
colon carcinoma (3 papers, 2016 to 2023). "Consistently, IMP3 was found to be highly expressed in approximately 75% of colon cancer samples (T) compared to healthy subjects (CTR)." (PMID 37024466, 2023). "IMP3−/− mice showed a statistically significant reduction in the total tumor area and in the number of colon tumors compared with IMP3fl/fl mice." (PMID 34154626, 2021). "The identification of a regulator such as IMP3 could explain the molecular mechanism that allows the up-regulation of Bcl-2 antiapoptotic protein expression in colon cancer." (PMID 37024466, 2023).
esophageal cancer (3 papers, 2012 to 2020). A primary or metastatic malignant neoplasm involving the esophagus. "Further, it has been shown that peptides derived from IMP3 induce immune response of helper T cells and cytotoxic T lymphocytes resulting in better clinical response in esophageal cancer." (PMID 28465487, 2017).
esophageal squamous cell carcinoma (3 papers, 2012 to 2022). Esophageal squamous cell carcinoma (ESCC) is a type of esophageal carcinoma (EC) that can affect any part of the esophagus, but is usually located in the upper or middle third. "Insulin-like growth factor-II mRNA-binding protein-3 (IMP3) is an important factor in carcinogenesis, although its clinical significance in esophageal squamous cell carcinoma (ESCC) remains unknown." (PMID 25295085, 2014).
leiomyosarcoma (3 papers, 2016 to 2024). An uncommon, aggressive malignant smooth muscle neoplasm, usually occurring in post-menopausal women. "IMP3 immunoreactivity in leiomyosarcoma also illustrates the more aggressive behavior of the tumor and predicts a worse prognosis." (PMID 38818470, 2024). "In regard to sarcomas, cytoplasmic IMP3 expression of varying intensity was detected in 52-100% of cutaneous leiomyosarcomas in contrast to typical leiomyomas." (PMID 26943575, 2016). "One extremely specific biomarker of leiomyosarcoma is IMP3, which may be involved in the pathophysiology of the disease." (PMID 38818470, 2024).
leukemia (3 papers, 2005 to 2022). A malignant (clonal) hematologic disorder, involving hematopoietic stem cells and characterized by the presence of primitive or atypical myeloid or lymphoid cells in the bone marrow and the blood. "The importance of IMP3 was recently emphasized in a study demonstrating by RNA interference its involvement for enhancing IGFII mRNA translation in K562 leukemia cells." (PMID 16129025, 2005). "IGF2BP3 (alias IMP3), represses translation of IGF-2 during late embryonic development in mice and humans, and has been shown to promote the translation of IGF-2 leader 3 mRNA in a cell model of leukemia." (PMID 23936243, 2013).
lymphoma (3 papers, 2016 to 2022). A malignant (clonal) proliferation of B- lymphocytes or T- lymphocytes which involves the lymph nodes, bone marrow and/or extranodal sites. "Previous research has illustrated that IGF2BP3 (IMP-3) overexpression is seemingly restricted to several epithelial malignancies correlated with aggressive behavior and lymphomas originating from physiologic germinal center B cells." (PMID 34802044, 2022). "In our study, IMP3 was expressed in the residual germinal centers of non-neoplastic lymphoid follicles of lymphoma cases, while other parts of lymphoid follicles were negative." (PMID 36577979, 2022). "On the other hand, 8–20% of the lymphomas with the origin of non-germinal center (marginal zone, mantle cell, small lymphocytic, B lymphoblastic and anaplastic large cell lymphoma) were positive for IMP3." (PMID 36577979, 2022).
non-small cell lung carcinoma (3 papers, 2010 to 2015). A group of at least three distinct histological types of lung cancer, including non-small cell squamous cell carcinoma, adenocarcinoma, and large cell carcinoma. "According to these articles, IMP3 overexpression in high grade neuroendocrine carcinoma, non small cell lung carcinoma and adenocarcinoma correlated with poor differentiation and advanced stage of disease." (PMID 23190601, 2012). "In addition, a first phase I clinical trial with an anti-IMP3 immunotherapy in non-small cell lung cancer showed a high level of safety and so potentially offers a new therapeutic option for other malignancies as well." (PMID 20591150, 2010). "In the group of non small cell lung cancer - not otherwise specified, adenocarcinoma phenotype can be determined immunohistochemically using TTF-1 and Napsin A. Expression of oncofetal protein IMP3 in human cancer is associated with poor differentiation and aggressive behaviour." (PMID 23190601, 2012).
ovarian serous carcinoma (3 papers, 2015 to 2022). "Our prior study showed that IMP3 may serve as a complimentary biomarker in diagnosing STIC and overexpression of IMP3 in tubal epithelia increases the risk of ovarian serous cancer development." (PMID 27733814, 2016). "Overexpression of IMP3 is associated with an unfavorable overall survival of patients with epithelial ovarian carcinoma (EOC), such as ovarian clear cell carcinoma (OCCC), ovarian serous carcinoma and primary ovarian mucinous carcinoma." (PMID 35706003, 2022).